ASB5 (ankyrin repeat and SOCS box containing 5)
Description:
May be a substrate-recognition component of a SCF-like ECS (Elongin-Cullin-SOCS-box protein) E3 ubiquitin-protein ligase complex which mediates the ubiquitination and subsequent proteasomal degradation of target proteins. May play a role in the initiation of arteriogenesis (By similarity).
Synonyms: ASB-5
Tractability: Antibody: the Human Protein Atlas places it where antibodies can reach.
Gene: Protein-coding gene on chromosome 4 (176,213,673 to 176,277,571, reverse strand). Ensembl gene ENSG00000164122.
Subcellular location (Human Protein Atlas): Plasma membrane
Pathways (Reactome):
Immune System: Antigen processing: Ubiquitination & Proteasome degradation
Metabolism of proteins: Neddylation
Gene Ontology:
Biological process: positive regulation of protein catabolic process; protein ubiquitination; intracellular signal transduction
Cellular component: cytosol
Genetic constraint (gnomAD): Loss-of-function variants: 40 observed, 39.53 expected, observed/expected ratio (o/e) 1.01, 90% interval 0.79 to 1.32. The upper end of that interval is the gene's LOEUF score, 1.32, which puts it in group 5 of 6, group 1 being the genes least tolerant of losing a copy. Missense variants: 393 observed, 408.47 expected, observed/expected ratio (o/e) 0.96, 90% interval 0.88 to 1.05. Synonymous variants: 146 observed, 155.37 expected, observed/expected ratio (o/e) 0.94, 90% interval 0.82 to 1.08.
Homologues: Orthologues: chimpanzee ASB5 (100% identical), rabbit ASB5 (96% identical), mouse Asb5 (94% identical), dog ASB5 (93% identical), rat Asb5 (92% identical), pig ASB5 (92% identical), guinea pig ASB5 (91% identical), macaque ASB5 (89% identical), tropical clawed frog asb5 (82% identical). Paralogues in human: ASB11 (53% identical), ASB9 (43% identical).
Diseases named in the same sentence as ASB5 in open-access papers:
ASB5 is named in the same sentence as 5 diseases in open-access papers, as found by Europe PMC text mining. Sharing a sentence is not in itself a finding about the gene and the disease. The quoted sentences say what the papers report.
epilepsy (1 paper, 2018). A brain disorder characterized by episodes of abnormally increased neuronal discharge resulting in transient episodes of sensory or motor neurological dysfunction, or psychic dysfunction. "Moreover, PTPRM, PPFIA1, SLC1A2, and SGCE were confirmed to be associated with epilepsy, while PTPRD, ASB5, and MCU were involved in neurological disorders." (PMID 29568349, 2018).
gastric cancer (1 paper, 2024). A primary or metastatic malignant neoplasm involving the stomach. "Additionally, in gastric cancer, high expression of ankyrin repeat and SOCS box-containing 5 (ASB5), secreted frizzled-related protein 1 (SFRP1), SMYD1, and tachykinin receptor 2 (TACR2) is associated with short survival times and high risk in these patients." (PMID 39482529, 2024).
ASB5 also shares sentences with these, for which no sentence is quoted: Chagas disease (1 paper); heart diseases (1); neurological disorders (1).